IGF1R (insulin like growth factor 1 receptor)
Diseases named in the same sentence as IGF1R in open-access papers (continued):
Sharing a sentence is not in itself a finding about the gene and the disease.
Ewing sarcoma (continued). "The application of these tools has previously revealed means of response and resistance in two cases of refractory Ewing sarcoma that responded to combination therapy with insulin-like growth factor 1 receptor and mTOR inhibition." (PMID 26444865, 2015). "IGF1R is a RTK involved in Ewing Sarcoma development and its therapeutic inhibition has shown promising preclinical results." (PMID 26712767, 2015). "Aberrant fusion products, such as EWS-WT1 or EWS-FLI, the genetic hallmarks of desmoplastic small round cell tumor or Ewing sarcoma, were found to act as transactivators for the IGF-1R system, providing a selective growth advantage to tumor cells." (PMID 25906745, 2015). "In a small study that sequenced the tumors of a few patients, it was intriguing that PTPRD germline aberrations conferred clinical benefit to patients with Ewing sarcoma who received therapy directed at the IGF1R and mTOR pathway." (PMID 26510912, 2015). "In Ewing’s sarcoma cell lines that acquired resistance to anti-IGF-1R mAbs and TKIs, overexpression of INSR-A homodimer and/or IGF-2 production was observed." (PMID 26217584, 2015). "Increased Akt phosphorylation was also observed in anti-IGF1R resistant Ewing sarcoma cell lines and tumors." (PMID 26402468, 2015). "The aim of this project was to validate RTK RON as therapeutic target in Ewing Sarcoma, alone and in combination with IGF1R inhibition." (PMID 26712767, 2015). "Other IGF-1R inhibitor studies have demonstrated mixed or partial responses in patients with Ewing’s Sarcoma and neuroendocrine tumors." (PMID 24458261, 2014). "In order to evaluate the degree of IGF-1R overexpression in Ewing sarcoma cells, we assessed relative IGF-1R surface expression in ES cell lines and NWTb3 cells, the NIH-3T3 cell line transfected to overexpress human IGF-1R, using flow cytometry." (PMID 23431249, 2013). "The insulin-like growth factor 1 receptor (IGF-1R) has been considered an important therapeutic target in Ewing sarcoma (ES), generating a need to identify the subset of patients most likely to respond to IGF-1R inhibitors." (PMID 23431249, 2013). "At the time these preclinical studies were published, early clinical trials of anti-IGF-1R therapy were already under way in patients with Ewing sarcoma." (PMID 23431249, 2013). "MDM2-mediated ubiquitination of IGF-1R with PPP treatment leads to the activation of ERK pathway, resulting in the resistance of Ewing’s sarcoma to the treatment of the anti-IGF-1R antibody figitumuab." (PMID 24182354, 2013). "Testing by the Pediatric Preclinical Testing Program further demonstrated that growth of some Ewing sarcoma cell lines is inhibited by IGF-1R inhibition." (PMID 23383402, 2013). "All coding exons of IGF1R were subjected to Sanger sequencing in DNAs from 47 tumor samples of Ewing sarcoma (all fusion verified) and 8 Ewing sarcoma cell lines (TC71, A4573, TC32, SK-PN-DW, SK-ES-1, RDES, A673, and CHP100)." (PMID 23431249, 2013). "The Pediatric Preclinical Testing Program (PPTP) reported mixed results of anti-IGF-1R treatments developed for clinical use in Ewing sarcoma xenograft models; these were evaluated with larger starting tumor volumes, between 200 and 500 mm3." (PMID 23431249, 2013). "Initial preclinical testing showed that murine monoclonal antibody alphaIR3, an IGF-1R antagonist, slows in vivo growth of Ewing sarcoma cells in mice." (PMID 23383402, 2013). "In clinical studies with IGF-1R antagonists alone, responses in patients were seen in some Ewing sarcoma patients and in isolated cases in patients with other cancers." (PMID 23383402, 2013). "IGFBP3 was highly downregulated in three out of four analyses, and has been shown to elicit anticancer effects by inhibiting IGF1R signaling in Ewing sarcoma." (PMID 23688189, 2013).
Ewing sarcoma (continued). "The promise of IGF-1R inhibition as a treatment for Ewing sarcoma garnered remarkable enthusiasm over the course of the past two decades." (PMID 23431249, 2013). "Monoclonal antibodies against IGF1R have modest activity against Ewing sarcoma, as was observed in a phase I/II study of figitumumab (partial response in 14.2% of all subjects) and in a phase II study using R1507 (complete/partial response rate of 10%)." (PMID 23688189, 2013). "Because phosphorylated STAT3 is frequently upregulated in Ewing sarcoma and PTPRD dephosphorylates STAT3, the role of germline and somatic PTPRD mutations in Ewing sarcoma as well as the implications for IGF-1R targeted therapy warrant exploration." (PMID 23800680, 2013). "As in Ewing sarcoma, rhabdomyosarcoma cell lines have demonstrated sensitivity to IGF-1R inhibition." (PMID 23383402, 2013). "Twenty-nine patients with Ewing’s sarcoma and a heterogeneous group of other sarcoma subtypes were treated with single agent figitumumab (CP-751, 871, Pfizer, IgG2 monoclonal antibody to IGF-1R) using a dose of 20 mg/kg every 3 weeks." (PMID 22415797, 2012). "Clinical trials in patients with Ewing sarcoma showed approximately 10–15% response rate following single-agent treatment with IGF-1R antibody targeting EWS-FLI1 or EWS-ERG." (PMID 22577336, 2012). "Clinical validation of IGF-1R as a target emerged with early evidence of activity, especially in Ewing’s sarcoma and other sarcoma subtypes, ACC and NSCLC." (PMID 22415797, 2012). "A phase II trial investigating the efficacy of SCH-717454 (robatumumab, a fully human neutralizing anti IGF-1R antibody) has planned to include 190 patients with osteosarcoma and Ewing’s sarcoma family of tumors." (PMID 22415797, 2012). "Insulin-like growth factor-1 receptor (IGF-1R) antagonists have demonstrated modest single agent efficacy in phase I/II clinical trials in Ewing sarcoma/PNET, but have a strong preclinical rationale." (PMID 22587874, 2012). "Early clinical data suggested the activity of IGF-1R target-drugs in selected tumor types, such as Ewing’s sarcoma, non-small cell lung cancer, adrenocortical carcinoma, but the initial enthusiasm quickly encountered several challenges and disappointment." (PMID 22415797, 2012). "IGF1R is targeted by miR-145 and miR-31*, and previous studies have shownIGF1R to be a direct target of miR-145 as well as to be over-expressed in Ewing tumors." (PMID 22429812, 2012). "CP-751,871, a human IGF-1R blocker, showed significant growth inhibition in Ewing sarcoma-bearing mice." (PMID 22577336, 2012). "This pilot study assessed two patients with advanced Ewing's sarcoma treated with IGF1R antibody alone followed by combined IGF1R inhibitor plus mammalian target of rapamycin (mTOR) inhibitor treatment once resistance to single-agent IGF1R inhibitor developed." (PMID 21494688, 2011). "Work by Scotlandi and colleagues revealed that IGF-1R system was activated in Ewing's sarcoma cell lines and tumours by an autocrine loop." (PMID 21647361, 2011). "HSP90 was differentially expressed between Ewing's sarcoma cell lines sensitive versus resistant to treatment and HSP90 inhibition reduced Ewing's sarcoma cell line growth and survival, especially in the cell lines resistant to IGF1R inhibitors." (PMID 21437217, 2011). "The growth of two Ewing's sarcoma cell lines (TC-32 and TC-71) was inhibited by the fully human anti-IGF-1R antibody, R1507 (clonogenic and MTT assays)." (PMID 22022506, 2011). "Signaling through the insulin-like growth factor type I receptor (IGF-1R) is critical for the growth and maintenance of Ewing sarcoma cells, and its inhibition offers an attractive new target for therapy." (PMID 21512587, 2011). "Inhibition of IGF-1R signalling has been shown to increase the sensitivity of Ewing's sarcoma cells to chemotherapy." (PMID 21647361, 2011).
Ewing sarcoma (continued). "In the case of Ewing's sarcoma, IGF-1R is ubiquitously expressed and its activation is sustained by the autocrine production of IGF1 by tumour cells." (PMID 21647361, 2011). "Inhibition of IGF1R and/or IGF1R and mTOR has resulted in significant clinical activity in patients with Ewing's sarcoma." (PMID 21494688, 2011). "Two patients with Ewing's sarcoma who responded, but then progressed after IGF1R inhibitor therapy alone showed consistently high mTORC2 expression in their tumors." (PMID 21494688, 2011). "Insulin-like growth factor 1 receptor (IGF1R) targeted therapies have resulted in responses in a small number of patients with advanced metastatic Ewing's sarcoma." (PMID 21494688, 2011). "EWS-FLI1 fusion protein, the hallmark of Ewing's sarcoma, downregulates insulin-like growth factor binding protein 3, IGFBP3, and upregulates IGF-1 expression resulting in enhanced IGF1R." (PMID 21494688, 2011). "Even so, phase I studies with different IGF1R antibodies demonstrated remarkable responses in a subset of Ewing's sarcoma patients." (PMID 21494688, 2011). "In vitro studies have shown that IGF-1R is directly involved in Ewing's sarcoma cell proliferation and survival." (PMID 21647361, 2011). "These in vitro results have been confirmed with the finding of IGF-1R expression in clinical samples of Ewing's sarcoma and the demonstration that lower levels of IGF-1R expression correlate with a lower tumor proliferative rate and a better prognosis." (PMID 21647361, 2011). "The activity of IGF1R monoclonal antibodies has been confirmed by the early reports of clinical activity in Ewing sarcoma." (PMID 21437217, 2011). "Herein, we report our experience with two index cases of Ewing's sarcoma, with an initial positive response to an IGF1R inhibitor followed by resistance." (PMID 21494688, 2011). "A subset of patients with Ewing's sarcoma responds to anti-insulin-like growth factor-1 receptor (IGF-1R) antibodies." (PMID 22022506, 2011). "During the last two decades, large amounts of preclinical data have been accumulated supporting the use of agents targeting IGF-1R in Ewing's sarcoma." (PMID 21647361, 2011). "The insulin-like growth factor 1 receptor (IGF-1R) has been implicated in the genesis, growth, proliferation, and the development of metastatic disease in Ewing's sarcoma." (PMID 21647361, 2011). "We performed morphoproteomic profiling to better understand response/resistance mechanisms of Ewing's sarcoma to IGF1R inhibitor-based therapy." (PMID 21494688, 2011). "Insulin-like growth factor 1 receptor (IGF1R)-targeted therapies have shown early promise, with responses in a small number of patients with Ewing's sarcoma." (PMID 21494688, 2011). "Subsequently, Prieur and colleagues demonstrated the potential role of the EWS-FLI1 fusion protein in Ewing's sarcoma in the IGF-1R pathway activation by repressing IGF-binding proteins." (PMID 21647361, 2011). "Ewing Sarcoma cell lines are highly sensitive to IGF1R inhibitors, especially in combination with conventional chemotherapy." (PMID 21197471, 2011). "Early clinical trials using anti-IGF1R monoclonal antibodies showed promising results in refractory Ewing's sarcomas and rhabdomyosarcomas." (PMID 19034281, 2008). "However, as more patients with Ewing sarcoma were enrolled onto clinical trials, it became clear that objective response rates for anti-IGF1R MABs were generally in the 10 % to 15 % range for Ewing sarcoma and that most responses were not prolonged." (PMID 39510293, 2024). "Rhabdomyosarcoma and Ewing sarcoma cell lines used by the PPTPC/C were employed to develop evidence for an alternative mechanism of resistance to anti-IGF1R MABs, that being that both intrinsic and acquired resistance are a consequence of redundant signaling by other receptor tyrosine kinases." (PMID 39510293, 2024).
Ewing sarcoma (continued). "On the contrary, however, inhibition of the IGF1R signaling pathway using an IGF1R-specific antibody is reported to enhance NK cell expansion following their activation and to maintain their potent cytotoxic activity in vitro against Ewing sarcoma." (PMID 38420122, 2024). "EV-miRNA profiling revealed that IGF2BP3 silencing of Ewing’s sarcoma cells altered specific miRNAs associated with the PI3K/Akt pathway in recipient cells, including miR-223-3p which target IGF1R, a major driver of EWS aggressiveness and a previously reported target of IGF2BP3." (PMID 38730633, 2024). "For instance, post-hoc analyses of pre- and post-treatment biopsy samples from Ewing sarcoma patients treated with either IGF-1R mAb or a combination of cixutumumab and the mTOR inhibitor temsirolimus revealed that median PFS and OS was better in phospho-IGF-1R-negative patients." (PMID 37858153, 2023). "After IGF-1R is activated and overexpressed in Ewing sarcoma, it may have a synergistic effect on the fusion gene EWS-FLI1, thus driving the occurrence of Ewing sarcoma." (PMID 35680570, 2022). "It is also plausible that single-agent IGF-1R-directed monoclonal antibodies and small molecule inhibitors are not effective enough to fully abrogate downstream mTOR signaling, as demonstrated in Ewing sarcoma preclinical models." (PMID 35284040, 2022). "Sarcomas, particularly Ewing sarcoma and osteosarcoma have overexpression of IGF1R." (PMID 36457575, 2022). "It was reported that the IGF-1R pathway is activated in several cancers, such as hepatocellular carcinoma, pancreatic ductal carcinoma, retinoblastoma, colorectal cancer, and Ewing sarcoma." (PMID 35454895, 2022). "IGF-1R exerts an enormous function on the genesis and evolution of Ewing sarcoma." (PMID 35680570, 2022). "At present, IGF-1R inhibitors have good clinical effects on Ewing sarcoma in the clinic." (PMID 35680570, 2022). "Also, osteosarcoma and Ewing sarcoma tumors expressed higher level of IGF-1R compared to GCT tumors (P < 0.0001); while the difference between osteosarcoma and Ewing sarcoma tumors was not remarkable." (PMID 36713521, 2022). "Ewing sarcoma cells express high amounts of IGF1R on their surface." (PMID 35220407, 2022). "Additionally, we observed cancer-type-specific correlations between dependency scores of pairs of genes in the IGF1R pathway in neuroblastoma and Ewing’s sarcoma." (PMID 35382456, 2022). "To show general applicability, we used the modular platform for IGF1R-positive Ewing sarcomas." (PMID 35220407, 2022). "In Ewing sarcoma cells, constitutive activation of the IGF1R confers resistance to inhibitors of the family of bromodomain and extra-terminal domain (BET) proteins, which recognize acetylated histone marks, thus recruiting supramolecular complexes to promote active transcription." (PMID 33673232, 2021). "Published data indicated that nuclear localization of the IGF1R, evaluated by immunohistochemistry in different sarcoma specimens including Ewing sarcoma might work as a predictive marker of response to anti-IGF1R mAbs." (PMID 34440844, 2021). "Similarly to Ewing sarcoma, the identification of biomarkers predictive of response in patients most likely to benefit from anti-IGF1R therapy remains elusive at this time." (PMID 34440844, 2021). "Similarly, compensatory up-regulation of IRS-1, PI3K, STAT3 and p38 MAPK emerged as mechanisms of resistance to different IGF1R inhibitors in Ewing sarcoma." (PMID 34440844, 2021). "Given the emerging role of RON in carcinoma progression and metastasis, but a lack of data characterizing RON in (any) sarcoma, we aimed to explore RON functions and its potential as a therapeutic target in Ewing sarcoma, alone and in its interaction with IGF1R." (PMID 32272784, 2020). "IGF1R was early identified as a target in Ewing sarcoma, as the IGF1R was highly expressed in Ewing sarcoma cell lines in addition to the expression of IGF1, which may thus signal in an autocrine loop." (PMID 33260481, 2020).
Ewing sarcoma (continued). "Second, as the IRA is expressed in Ewing sarcoma cell lines and other solid tumors, blocking the IGF1R alone could be insufficient to achieve clinical benefit." (PMID 33260481, 2020). "Another IGF1-R inhibitor is ganitumab, whose efficacy against Ewing sarcoma was evaluated." (PMID 31963219, 2020). "Additionally, the IGF1R inhibition experiments reduced the growth of Ewing sarcoma both in vitro and in vivo." (PMID 33260481, 2020). "Moreover, a recent article has provided as proof-of-concept the combination of NHWD-870 with agents targeting the IGF1R pathway for treating advanced Ewing sarcoma." (PMID 31231611, 2019). "IGF1R-targeted therapies for many solid tumors (including Ewing sarcomas) have been investigated." (PMID 30487384, 2018). "The fusion gene includes EWSR1 in chromosome 22 (as noted in the earlier section about Ewing sarcomas), and thus IGF1R expression might be a clue for distinguishing CCS from melanoma." (PMID 30487384, 2018). "IGF-1 and IGF-1R expression are elevated in Ewing sarcoma cell lines and tumors." (PMID 29321818, 2017). "Anti-IGF1R therapy has shown efficacy in a small subset of Ewing sarcoma patients." (PMID 27259270, 2016). "In addition, four chondrosarcoma cell lines and the Ewing sarcoma cell line were treated with two other IGF1R/IR inhibitors (NVP-ADW742 and GSK1838705A) to determine if alternative targeting showed similar effects on cell viability." (PMID 27418340, 2016). "During the time period of this study, additional Ewing sarcoma patients were treated on phase I trials of IGF-1R therapies within the Pediatrics and Sarcoma Medical Oncology Departments within our institution; however these patients were not captured in this analysis." (PMID 27486883, 2016). "To test whether this holds true in Ewing Sarcoma, we compared the efficacy of the IGF-1R small molecule inhibitor OSI-906 in PTEN-negative cells with and without ectopic PTEN expression." (PMID 25603314, 2015). "Although the single-agent response rates to IGF-1R antibodies in phase II trials have been generally disappointing [reviewed in 46], there have been occasional patients with impressive and durable responses in patients with Ewing sarcoma and rhabdomyosarcoma." (PMID 26322224, 2015). "In summary, our studies identify a growth-promotional role for PIK3R3 in Ewing Sarcoma, and provide evidence that loss of PTEN expression may diminish responsiveness to vincristine and IGF-1R blockade." (PMID 25603314, 2015). "IGF-1R signaling must be intact for Ewing sarcoma cell lines to proliferate." (PMID 23383402, 2013). "Interestingly, treatment targeted against IGF1R signaling has shown to be effective in a subset of Ewing sarcoma, another bone tumor that manifests at young age." (PMID 23688189, 2013). "IGF-1R inhibitors in Ewing sarcoma (adapted from Maki, 2012)." (PMID 23383402, 2013). "Since absolute IGF-1R levels are relatively low in ES cell lines, we sought to determine whether Ewing sarcoma stem-like cells constituted a population of cells resistant to anti-IGF-1R therapy based upon lower expression of IGF-1R than the total population." (PMID 23431249, 2013). "Ewing sarcoma cells consistently express IGF-1R and insulin receptor (IR)." (PMID 22577336, 2012). "In addition, IGF1-R has been validated, both in vitro and in vivo, as a potential therapeutic target in Ewing's sarcoma." (PMID 21647361, 2011). "The IGF1R antagonist, AMG 479, has shown promising results in the treatment of ESFTs in a phase I clinical trial, indicating that Ewing Sarcomas may be particularly sensitive to intervention of the IGF1R signaling pathway." (PMID 21197471, 2011). "We investigated whether an anti-IGF-1R antibody acts via a pathway that could also be suppressed by small interfering (si) RNA against the EWS/FLI-1 fusion protein, the hallmark of Ewing's sarcoma." (PMID 22022506, 2011).